PROX2 (prospero homeobox 2)
Description:
Transcription regulator. Does not seem to be essential for embryonic development and postnatal survival (By similarity).
Synonyms: PROX-2; FLJ36749
Tractability: No criterion of Open Targets' tractability assessment is met for any kind of drug.
Gene: Protein-coding gene on chromosome 14 (74,852,871 to 74,876,154, reverse strand). Ensembl gene ENSG00000119608.
Subcellular location: Nucleus
Gene Ontology:
Molecular function: DNA-binding transcription factor activity, RNA polymerase II-specific; RNA polymerase II cis-regulatory region sequence-specific DNA binding; DNA binding
Biological process: regulation of transcription by RNA polymerase II; anatomical structure formation involved in morphogenesis; cell fate commitment; central nervous system development; embryonic retina morphogenesis in camera-type eye; hepatocyte differentiation; lens fiber cell morphogenesis; lymphatic endothelial cell differentiation; pancreas development; regulation of DNA-templated transcription; tube development
Cellular component: chromatin; nucleus; cytoplasm
Genetic constraint (gnomAD): Loss-of-function variants: 44 observed, 45.36 expected, observed/expected ratio (o/e) 0.97, 90% interval 0.76 to 1.25. The upper end of that interval is the gene's LOEUF score, 1.25, which puts it in group 5 of 6, group 1 being the genes least tolerant of losing a copy. Missense variants: 622 observed, 686.59 expected, observed/expected ratio (o/e) 0.91, 90% interval 0.85 to 0.97. Synonymous variants: 247 observed, 262.26 expected, observed/expected ratio (o/e) 0.94, 90% interval 0.85 to 1.05.
Homologues: Orthologues: chimpanzee PROX2 (97% identical), macaque PROX2 (93% identical), pig PROX2 (74% identical), guinea pig PROX2 (71% identical), rat Prox2 (67% identical), mouse Prox2 (65% identical), rabbit PROX2 (63% identical), dog PROX2 (48% identical), zebrafish prox2 (35% identical), Drosophila melanogaster pros (29% identical), Caenorhabditis elegans pros-1 (20% identical). Paralogues in human: PROX1 (35% identical).
Diseases named in the same sentence as PROX2 in open-access papers:
PROX2 is named in the same sentence as 4 diseases in open-access papers, as found by Europe PMC text mining. Sharing a sentence is not in itself a finding about the gene and the disease. The quoted sentences say what the papers report.
cervical cancer (1 paper, 2023). A primary or metastatic malignant neoplasm involving the cervix. "The results showed that high expression of MYH1, MYH4, FGG, and DEPP1 was associated with shorter overall survival of patients with cervical cancer; high expression of SULT1E1, RAB3C, CXCR3, and PROX2 was associated with longer overall survival of patients with cervical cancer." (PMID 37350944, 2023). "On the other hand, high SULTIEI, RAB3C, CXCR3, PROX2, and KRT42P expression was associated with a better prognosis in cervical cancer." (PMID 37350944, 2023). "High expression of MYH1, MYH4, FGG, DEPP1, and ZBTB16 was associated with shorter overall survival of patients with cervical cancer; high expression of SULT1E1, RAB3C, CXCR3, and PROX2 was associated with longer overall survival of patients with cervical cancer." (PMID 37350944, 2023).
liver disease (1 paper, 2025). "In addition, state #5 was identified as PDPN, FOXC2, and PROX2-expressing lymphatic-specific ECs; state #6 as a subpopulation expressing PLAT, whose protein level is increased in patients with liver disease; and, states #23, #32 and #34 as liver-specific liver sinusoidal ECs (LSECs)." (PMID 39748128, 2025).
Obesity (1 paper, 2021). Accumulation of substantial excess body fat. "In the CD line, there were 18 overlapping selected markers and 19 genes from the two levels of which PROX2 was related to the BFT trait and located in the obesity index QTL region." (PMID 34557543, 2021).
PROX2 also shares sentences with these, for which no sentence is quoted: amyotrophic lateral sclerosis (1 paper).